COL4A1 (collagen type IV alpha 1 chain)
Diseases named in the same sentence as COL4A1 in open-access papers (continued):
Sharing a sentence is not in itself a finding about the gene and the disease.
Nephropathy (continued). "Hereditary angiopathy with nephropathy, aneurysms, and muscle cramps (HANAC) syndrome patients with COL4A1 glycine substitution mutations can develop mitral/aortic valve prolapse, with some requiring artificial valve replacement later in life." (PMID 34382650, 2021). "Monogenic COL4A1 syndrome due to mutations in COL4A1 or COL4A2 is a complex multisystemic disorder that includes ocular defects, intracerebral haemorrhage, cerebral small vessel disease, kidney disease, and muscle cramps." (PMID 34382650, 2021). "Col4a1 renal disease encompasses glomerular defects including hypertrophy of Bowman’s capsule and glomerulocystic kidney disease, as well as tubular defects that are associated with polyuria (increased urine production)." (PMID 30351356, 2019). "Col4a1 glomerulocystic kidney disease includes retraction of the capillary tuft, which was detected in ∼18% (19/103) of glomeruli in untreated mice and ∼15% (14/94) of treated mice." (PMID 30351356, 2019). "A distinct form of type IV collagenopathy, Hereditary Angiopathy, Nephropathy, Aneurysms, and Muscle Cramps (HANAC) syndrome, is caused by N-terminal mutations within the COL4A1 gene." (PMID 29651426, 2018). "Missense mutations of COL4A1 that encode the CB3 [IV] segment of the triple helical domain (exons 24 and 25) are associated with HANAC syndrome (hereditary angiopathy, nephropathy, aneurysms and cramps)." (PMID 27190376, 2016). "Mutations in the ubiquitous human BM components COL4A1 and COL4A2 cause a multisystem disorder involving nephropathy." (PMID 27077087, 2016). "Vascular BMs displayed extensive defects, including fragmentation and focal absence, likely causing vascular fragility, haemorrhage and haematuria, underscoring the vascular component of Col4a1 renal disease." (PMID 26839400, 2016). "Although subtle GBM defects are likely to contribute and indicate the importance of this network for renal function, it has also been proposed that Bowman's capsule, which is severely affected in Col4a1 renal disease, can act as a secondary barrier." (PMID 26839400, 2016). "Mutations in the extracellular matrix component collagen IV (Col4a1) cause cerebrovascular, eye and kidney disease, for which there are no treatments." (PMID 33745160, 2021). "A novel COL4A1 frameshift mutation was demonstrated to cause kidney disease without extra renal involvement in a large Turkish Cypriot family." (PMID 27190345, 2017). "Moreover, our data show that genetic background also influences the development of Col4a1 renal disease, which has also been observed for albuminuria." (PMID 26839400, 2016). "It will now also be important to establish if the lack of effectivity for Col4a1 renal disease also applies to other kidney pathologies due to mutations in BM components such as Alport syndrome, where PBA reduced ER stress in cells with COL4A5 missense mutations." (PMID 30351356, 2019). "However, the role of this essential BM component in renal pathophysiology remains relatively poorly characterized; for example, the potential progression of Col4a1 renal disease and its pathomolecular mechanisms are unknown." (PMID 26839400, 2016). "However, COL4A1 renal disease remains poorly characterized and its pathomolecular mechanisms are unknown." (PMID 26839400, 2016). "The spectrum of COL4A1-related disorders included porencephaly (OMIM 175780), Hereditary Angiopathy with Nephropathy, Aneurysm and Muscle Cramps (HANAC; OMIM 611773), and brain small vessel disease with hemorrhage (OMIM 607595)." (PMID 21527998, 2011). "Hereditary angiopathy with nephropathy, aneurysms, and muscle cramps (HANAC) syndrome is a COL4A1-related phenotype with an asymptomatic brain small-vessel disease and frequent systemic manifestations, as muscular cramps, kidney and retinal involvement, and Raynaud phenomenon." (PMID 34073306, 2021).
Nephropathy (continued). "This absence of a further decline in GFR indicates that COL4A1 renal disease is unlikely to progress to renal failure, which is supported by a limited reduction of GFR in humans with HANAC syndrome." (PMID 26839400, 2016). "Missense mutations of COL4A1 that disrupt the NC1 domain are associated with antenatal cerebral haemorrhage and porencephaly, but not kidney disease." (PMID 27190376, 2016). "COL4A2 is the obligatory protein partner of COL4A1 but in contrast to most COL4A1 mutations, the COL4A2 mutation does not lead to eye or kidney disease." (PMID 24001601, 2014). "Finally, absence of renal phenotypes in 3-month-old Col4a1+/Raw mice on a mixed genetic background confirms that genetic modifiers influence Col4a1 renal disease." (PMID 26839400, 2016). "However, PBA treatment did not alter eye and kidney defects, establishing tissue-specific outcomes of targeting Col4a1-derived ER stress, and therefore this treatment may not be applicable for patients with eye and renal disease." (PMID 30351356, 2019). "Based on our current data, the most likely patients are those with mild myopathy and those with clinical manifestations that overlap with some of the other COL4A1-related phenotypes described in non-MEB/WWS syndromes including porencephaly, renal disease and cerebrovascular disease." (PMID 21625620, 2011).
Stroke (27 papers, 2011 to 2025). Sudden impairment of blood flow to a part of the brain due to occlusion or rupture of an artery to the brain. "We presented a Mexican young female with leukodystrophy and recurrent stroke secondary to COL4A1 monogenic mutation." (PMID 37681221, 2023). "In this population-based cohort study of 454 756 individuals, NOTCH3, HTRA1, and COL4A1/2 variants causing monogenic cSVD were associated with increased stroke and dementia risk." (PMID 36300346, 2022). "Dominant missense mutations in the COL4A1 gene result in a rare familial stroke characterized by deep ICH, lacunar ischemic stroke, and WMH." (PMID 35401403, 2022). "NOTCH3, HTRA1, and COL4A1/2 pathogenic variants in monogenic stroke; Framingham cardiovascular risk; and ischemic stroke polygenic risk." (PMID 36300346, 2022). "Mutations in COL4A1 have been found to cause cerebral vasculature defects, migraine, stroke, and epilepsy." (PMID 36618441, 2021). "For example mutations in human Col4a1 cause the weakening of the major vasculature leading to life threatening aneurysms or stroke while mutations in murine Col4a1 and Col4a2 induce vascular defects causing internal bleedings and prenatal lethality." (PMID 23874219, 2013). "Recent studies have also revealed an association between mutations in exon 29 of COL4A1 and Axenfeld-Rieger anomaly with leukoencephalopathy and stroke." (PMID 21527998, 2011). "Regarding genetic disorders that may cause strokes, COL4A1 mutation was mentioned in nine articles, while COL4A2 was mentioned in four articles." (PMID 38790247, 2024). "After limiting our analyses to unrelated individuals with adjustment for FRS and PRS, variant carrier prevalence was consistent, and the disease associations, excluding the risk of any stroke associated with COL4A1/2 variants, remained significant (eTables 6-8 in the Supplement)." (PMID 36300346, 2022). "COL4A1 encodes a type IV collagen alpha protein, and COL4A1 mutations may present with small vessel disease and stroke, both of which also have migraine as a clinical feature." (PMID 32632093, 2020). "The mutation of the gene encoding for the α1 chain of collagen type IV, COL4A1, is responsible for a monogenic stroke syndrome (hemorrhagic and/or ischemic small vessel disease), whereas an intron variant of the same gene has been associated with increased risk of multifactorial stroke." (PMID 33066304, 2020). "Furthermore, COL4A1 malfunction has been associated with cerebral microangiopathy, the Axenfeld-Rieger anomaly, and leukoencephalopathy and stroke." (PMID 22441714, 2012). "Individuals with pathogenic variants in COL4A1 and COL4A2 had clinical stroke for which hemorrhagic events were the most common causes." (PMID 41311701, 2025). "While COL4A1 and COL4A2 were common denominators for most of the stroke subtypes, high-density lipoprotein was inversely associated with small vessel stroke." (PMID 39268810, 2024). "Genetic variants in COL4A1 and COL4A2 (encoding collagen IV alpha chain 1/2) occur in genetic and sporadic forms of cerebral small vessel disease (CSVD), a leading cause of stroke, dementia and intracerebral haemorrhage (ICH)." (PMID 39216230, 2024). "detected only three cases with pathogenic variants in other monogenetic diseases causing stroke (HTRA1, COL4A1) apart from NOTCH3." (PMID 36411388, 2023). "Hemorrhagic events (ICH, porencephaly, and intraventricular hemorrhage) were the most commonly reported stroke type among COL4A1/2 individuals, affecting 73% (118/161) and 100% (9/9) of stroke cases, respectively." (PMID 35699195, 2022). "Cognitive features were the most common clinical cerebral phenotype for 4 of 7 genes (HTRA1HomZ, COL4A2, HTRA1HetZ, and CTSA); stroke was the most common among individuals with COL4A1 and ADA2, and headache was most common among individuals with TREX1." (PMID 35699195, 2022).
Stroke (continued). "Both ICH and ischemic stroke were described for all cSVD genes, although the most common stroke subtype was hemorrhagic for COL4A1/2 and ischemic for the remaining genes." (PMID 35699195, 2022). "Variants in COL4A1 and COL4A2 have been reported in patients diagnosed with CP41–44, however genetic testing was generally only performed upon evidence of recurrent stroke or evolution of multi-systemic clinical phenotypes." (PMID 34531397, 2021). "Rare monogenic causes of stroke, such as mutations in NOTCH3 (linked to CADASIL), COL4A1, or HTRA1, may also be found with genetic testing." (PMID 40863347, 2025). "We can not exclude that variants in the COL4A1 miRNA-29-binding site contribute to the pathogenesis of sporadic stroke at low frequencies below ~ 0.2% or to specific stroke subtypes not sufficiently represented in our samples." (PMID 36786861, 2023). "Sequence analysis in two independent German sporadic stroke samples did not identify a single variant in the core COL4A1 miRNA-29-binding site (5′-GGTGCT-3′) in any of the 874 sequenced patients with sporadic stroke." (PMID 36786861, 2023). "COL4A1 miRNA-29-binding site variants do not contribute to a sizeable proportion of sporadic stroke." (PMID 36786861, 2023). "For COL4A1/2, variant status was not predictive of incident stroke (HR, 1.03; 95% CI, 0.42-2.03; P = .95)." (PMID 36300346, 2022). "We found no variants in the COL4A1 miRNA-binding site of sporadic stroke patients." (PMID 36786861, 2023). "Strong correlations have been found at the COL4A1/2, FOXC1FOXC1, and HTRA1 loci—genes essential in preserving the integrity of the cerebral microvasculature—indicating that small-vessel (lacunar) stroke is genetically unique." (PMID 40863347, 2025). "The frequency of clinical stroke ranged from 22% to 52% for 6 of 7 genes (COL4A2, 22% [9/41]; HTRA1HomZ, 30% [13/44]; ADA2, 33% [115/346]; COL4A1, 41% [161/390]; CTSA, 50% [7/14]; HTRA1HetZ, 52% [43/82]), while only 9% (11/123) of TREX1 individuals were reported to have suffered a clinical stroke." (PMID 35699195, 2022). "Col4a1+/SVC display increased levels of Iba1, a marker for neuroglial activation that is the initial step in the central nervous system inflammatory response following stroke, which was reduced in treated mice, supporting reduced cerebrovascular disease severity and neuroinflammation." (PMID 30351356, 2019). "In addition, while the patients examined in this study all harboured the same variant in COL4A1 3′UTR, the number of multiple infarctions and severity of leukoencephalopathy varied among these patients and was not correlated with the age at the first stroke episode." (PMID 37953842, 2023).
Leukoencephalopathy (26 papers, 2011 to 2026). This term describes abnormality of the white matter of the cerebrum resulting from damage to the myelin sheaths of nerve cells. "Pontine autosomal dominant microangiopathy and leukoencephalopathy is one of hereditary cerebral small vessel diseases caused by pathogenic variants in COL4A1 3′UTR and characterized by multiple small infarctions in the pons." (PMID 37953842, 2023). "WES identified a missense variant in COL4A1 (p.Gly382Ser) (Microangiopathy and leukoencephalopathy, MIM: 618564) with pathogenic in silico predictions." (PMID 35606766, 2022). "Familial porencephaly, leukoencephalopathy and small-vessel disease belong to the spectrum of disorders credited to dominant mutations in the gene encoding for type IV collagen alpha-1 (COL4A1)." (PMID 26351537, 2015). "Other genetic mutations known to be associated with similar clinically presenting diseases (FHM1 in CACNA1A, FHM2 in ATP1A2, and mutations within COL4A1 cause COL4A1-associated leukoencephalopathy) have been identified through follow-up testing requested by clinicians." (PMID 31915071, 2020). "Mutations in COL4A1 cause a wide spectrum of autosomal dominant disorders including porencephaly, brain small-vessel disease with hemorrhage, leukoencephalopathy, hereditary angiopathy with nephropathy, aneurysms and muscle cramp (HANAC) syndrome, and Walker–Warburg syndrome." (PMID 29137252, 2017). "Differential diagnosis of leukoencephalopathies with calcifications includes COL4A1-related disorders and primary familial brain calcifications with leukoencephalopathy." (PMID 35683020, 2022). "An identical variant in the COL4A1 3′UTR was observed in two patients with familial small vessel disease and the two selected patients, thereby confirming the pontine autosomal dominant microangiopathy and leukoencephalopathy diagnosis." (PMID 37953842, 2023). "Mutations in COL4A1 and COL4A2 cause highly penetrant cSVD as part of the multisystem disorder known as Gould syndrome, which includes cerebrovascular manifestations such as porencephaly, early-onset stroke, leukoencephalopathy, and intracerebral hemorrhage (ICH)." (PMID 41311701, 2025). "Therefore, the importance of both COL4A1 and COL4A2 screening was emphasized in patients showing recurrent intracerebral hemorrhage of unknown etiology, particularly if associated with leukoencephalopathy." (PMID 26351537, 2015). "Nevertheless, for SVD patients with a positive family history, an unusual extensive leukoencephalopathy, and an absence of NOTCH3, HTRA1, and COL4A1/A2 mutations, a molecular analysis of the CTSA gene should be considered." (PMID 31484286, 2019).
intracerebral hemorrhage (24 papers, 2014 to 2025). A cerebrovascular disorder characterized by bleeding into one or both cerebral hemispheres including the basal ganglia and the cerebral cortex. "Notch3 mutant mice have been characterised and shown to be similar to human CADASIL, while mutations in Col4a1 genes result in intracerebral haemorrhages in mice and humans, and patients with Col4a1 mutations display white matter defects." (PMID 39543785, 2024). "Cerebrovascular disease, which regularly manifests as porencephaly, small-vessel disease and recurrent intracerebral haemorrhages, is associated with mutated COL4A1 and COL4A2 mutations." (PMID 39707430, 2024). "The COL4A1 gene, in association with COL4A3, are necessary for maturation of type IV collagen, and COL4A1 mutations cause cerebral small vessel disease, i.e., intracerebral hemorrhage and shortened life-span." (PMID 37194065, 2023). "Here, we screened the COL4A1 variants in Chinese intracerebral hemorrhage (ICH) patients to summarize the relationship between the variants and clinical characteristics." (PMID 35711275, 2022). "Association between alleles of COL4A1 and the death at 1-year follow-up in intracerebral hemorrhage patients." (PMID 35711275, 2022). "Mutations of Col4a1 in mice recapitulate theclinical spectrum of disease, including intracerebral hemorrhages, retinal vasculartortuosity and glomerular basement membrane defects." (PMID 28153846, 2017). "Perinatal intracerebral hemorrhage associated with COL4A1 gene mutations." (PMID 38978838, 2024). "Mutations in COL4A1/2 have been associated with brain malformations and intracerebral hemorrhage." (PMID 39640361, 2024). "NOTCH3 carriers had increased vascular dementia risk (OR, 5.42; 95% CI, 3.11-8.74), HTRA1 carriers an increased all-cause dementia risk (OR, 2.17; 95% CI, 1.28-3.41), and COL4A1/2 carriers an increased intracerebral hemorrhage risk (OR, 3.56; 95% CI, 1.34-7.53)." (PMID 36300346, 2022). "In some cases, genetic variation may be the cause of or a contributor to these precipitants: for example, individuals with COL4A1 mutations have high susceptibility to intracerebral haemorrhage." (PMID 31700678, 2019). "This increase in risk is primarily via ischemic stroke for NOTCH3 and HTRA1 and via intracerebral hemorrhage for COL4A1/2." (PMID 36300346, 2022). "Common genetic variants in COL4A1 and COL4A2 have been associated with intracerebral haemorrhage (ICH) in the general population while rare mutations, mostly affecting glycine resides, cause the hereditary COL4A1 syndrome." (PMID 33745160, 2021). "We previously characterized a mouse model of Gould syndrome caused by a Col4a1 mutation in which the severities of ocular anterior segment dysgenesis (ASD), myopathy and intracerebral hemorrhage (ICH) were dependent on genetic background." (PMID 34424299, 2021). "Col4a1 and Col4a2 mutant mice model mirror several types of human disease such as anterior segment ocular dysgenesis, glomerulopathy and spontaneous intracerebral hemorrhage." (PMID 33918807, 2021). "Choi highlighted phenotypic similarities between COL4A1 SVD and NOTCH3 mutations in CADASIL, showing that both conditions cause lacunar infarcts, cognitive deficits, intracerebral haemorrhage and migraine." (PMID 31915071, 2020). "COL4A1/COL4A2 mutations cause a multi-systemic disorder encompassing cerebrovascular disease, including intracerebral haemorrhage (ICH), as well as eye and renal defects including HANAC syndrome." (PMID 30351356, 2019). "Mutations in the collagen genes COL4A1 and COL4A2 cause Mendelian eye, kidney and cerebrovascular disease including intracerebral haemorrhage (ICH), and common collagen IV variants are a risk factor for sporadic ICH." (PMID 30351356, 2019). "We show the efficacy of long-term 4PBA treatment in reducing the severity of intracerebral hemorrhages (ICHs) in Col4a1 mutant mice aged up to 8 months." (PMID 29895609, 2018).
intracerebral hemorrhage (continued). "Furthermore, missense mutations in COL4A1/COL4A2 caused rare familial forms of cerebral SVD, manifesting as deep intracerebral hemorrhages, lacunar ischemic strokes, and WMHs." (PMID 31484286, 2019). "In addition to prenatal and perinatal hemorrhages, COL4A1 and COL4A2 mutations also caused the sporadic and recurrent intracerebral hemorrhages (ICH) in young and old patients." (PMID 31484286, 2019). "Microbleeds occur in both CADASIL and CADASIL2 but are particularly frequent in the COL4A1/2 monogenic forms of SVD, which also frequently present with intracerebral hemorrhage." (PMID 38044814, 2024). "While mice with biallelic splice mutations of exon 41 of Col4a1 are not viable, offspring with one mutated allele exhibit porencephaly and intracerebral haemorrhage which presents as fully penetrant multi-focal and recurrent intracerebral haemorrhage as adults." (PMID 39707430, 2024).